TRIM8 (tripartite motif containing 8)
Diseases named in the same sentence as TRIM8 in open-access papers (continued):
Sharing a sentence is not in itself a finding about the gene and the disease.
cervical cancer (1 paper, 2022). A primary or metastatic malignant neoplasm involving the cervix. "Experimental verification confirmed the inhibition of cervical cancer cells proliferation by lowering TRIM8 expression." (PMID 36353542, 2022). "This study explored the significance of TRIM8 in cervical cancer through tissue samples and cell lines." (PMID 36353542, 2022). "Multivariate Cox regression analysis found that lymph node metastasis (p=0.001) and TRIM8 expression (p=0.028) were independent prognostic factors for the survival of cervical cancers." (PMID 36353542, 2022). "DNA repair (A), collagen formation (B), degradation of ECM (C), angiogenesis (D), apoptosis (E), and TGF-β (F) were enriched in cervical cancer samples with high TRIM8 expression." (PMID 36353542, 2022). "Then, we used the online database to further explore TRIM8, evaluated the potential therapeutic drugs, and verified the biological role of TRIM8 in cervical cancer cells through cell function experiments." (PMID 36353542, 2022). "It was found that the interference of TRIM8 significantly reduced the proliferation, and increased the apoptosis of cervical cancer cells, which shared previous research results." (PMID 36353542, 2022). "The effect of TRIM8 on apoptosis of cervical cancer was detected by flow cytometry, which showed that compared with the control group, the silence of TRIM8 increased the apoptosis ratio of SiHa and HeLa cells (P< 0.001)." (PMID 36353542, 2022). "The immunohistochemical staining score of TRIM8 in cervical cancers was divided into high and low groups by median method." (PMID 36353542, 2022). "Accordingly, the association between the prognosis of cervical cancers and FIGO stage (P<0.001), depth of invasion (p=0.008), lymph node metastasis (p=0.006), postoperative adjuvant therapy (p=0.042), and TRIM8 expression (p=0.010) was validated." (PMID 36353542, 2022). "We extracted genes associated with both ubiquitination and autophagy from the key modules of weighted gene co-expression network analysis (WGCNA), and the analysis showed that TRIM8 was of great significance for the diagnosis and prognosis of cervical cancer." (PMID 36353542, 2022). "Among 176 cervical cancer tissues, 88 cases had high expression of TRIM8, and 88 cases had low expression." (PMID 36353542, 2022). "Kaplan Meier analysis was used to discover the relationship between TRIM8 expression and overall survival of patients, which confirmed that cervical cancers with high TRIM8 expression had a shorter overall survival, while those with low TRIM8 expression had a longer overall survival (p=0.0028)." (PMID 36353542, 2022). "Therefore, we studied the effect of TRIM8 on the proliferation of cervical cancer cells in SiHa and HeLa by CCK8 and clone formation experiment." (PMID 36353542, 2022). "Therefore, TRIM8 can be adopted as a new biomarker of cervical cancer to develop new therapeutic targets." (PMID 36353542, 2022). "We identified a biomarker (TRIM8) that may be related to cervical cancer through a series of analyses on the GEO dataset." (PMID 36353542, 2022). "IHC staining was first performed on the cancer and corresponding normal tissues of 176 patients with cervical cancer in tissue microarray, and TRIM8 expression in the nucleus and cytoplasm was confirmed, revealing the higher expression in cervical cancer than that in corresponding normal tissues." (PMID 36353542, 2022). "The χ2 test was used to analyze the relationship between TRIM8 and the clinicopathological characteristics of cervical cancers, demonstrating the close relation between high TRIM8 and FIGO stage (p=0.012), tumor size (P<0.001), and lymph node metastasis (P=0.034)." (PMID 36353542, 2022). "Relationship between TRIM8 and clinical characteristics of cervical cancers." (PMID 36353542, 2022). "Besides, experimental validation showed the high TRIM8 expression in cervical cancer, as well as its involvement in the proliferation of cervical cancer cells." (PMID 36353542, 2022).
cervical cancer (continued). "Therefore, this study aims to clarify the potential role of TRIM8 in cervical cancer." (PMID 36353542, 2022). "In order to identify the potential substrate of TRIM8, TRIM8, as the ligase substrate of E3, was queried in the web tool of UbiBrowser to identify the ubiquitinated protein target of TRIM8 that is overexpressed or underexpressed in the progression of cervical cancer." (PMID 36353542, 2022). "Therefore, the TRIM8 gene was found to be involved in the proliferation of cervical cancer." (PMID 36353542, 2022). "Finally, the combination of univariate and multivariate analysis showed that TRIM8 expression could be used as an independent prognostic factor for patients with cervical cancer." (PMID 36353542, 2022).
Crohn's colitis (1 paper, 2025). Crohn's disease affecting the colon. "This study elucidates a pathogenic pathway in which ITLN1 competitively binds TRIM8 to inhibit CAPN2 ubiquitination and degradation, stabilizing CAPN2 to promote ZBP1-mediated PANoptosis in IECs and exacerbate Crohn's colitis." (PMID 40520022, 2025).
ischemia (1 paper, 2021). A hypoperfusion of the BLOOD through an organ or tissue caused by a PATHOLOGIC CONSTRICTION or obstruction of its BLOOD VESSELS, or an absence of BLOOD CIRCULATION. "The suppression of TRIM8 expression, as well as of the NF-κB pathway, significantly reduces inflammation induced by ischemia, cerebral cognitive disability, apoptosis in the peri-hematoma cortex and the hippocampus." (PMID 33807506, 2021).
kidney cancer (1 paper, 2020). Primary or metastatic malignant neoplasm involving the kidney. "The expression levels of TRIM8 were substantially lower in kidney cancer tissues than in normal tissues." (PMID 33173411, 2020).
lupus nephritis (1 paper, 2025). Glomerulonephritis in the context of systemic lupus erythematosus. "The ROC curve analysis for the relative quantification (RQ) of TRIM8-associated ncRNA regulatory network markers revealed significant discriminatory power between active and non-active lupus nephritis patients." (PMID 41194165, 2025).
lymph node metastasis (1 paper, 2022). "Then, the expression of TRIM8 was statistically analyzed with the clinicopathological characteristics of patients, which confirmed the association between TRIM8 expression and tumor size, FIGO stage, and lymph node metastasis." (PMID 36353542, 2022).
macrophage activation syndrome (1 paper, 2022). A complication of rheumatic disease that is caused by excessive activation and uncontrolled proliferation of T lymphocytes and well-differentiated macrophages. "Participates in multiple biological processes including cell survival, differentiation, apoptosis, and in particular, the innate immune response.TRIM8 as a mediator of IFN-γ responsiveness and macrophage activation syndrome." (PMID 36204002, 2022).
metastatic tumors (1 paper, 2022). "Overall, the three most highly expressed genes are TRIM28, TRIM44, and TRIM8 in the primary and metastatic tumors and normal tissues." (PMID 35928444, 2022).
muscular dystrophies (1 paper, 2022). "Among these candidate genes were DNAJB12, HDAC5, and TRIM8, each belonging to a protein family that is being studied in the context of neurological disorders or muscular dystrophies." (PMID 36352383, 2022).
nephrotic syndrome (1 paper, 2021). A collection of symptoms that include severe edema, proteinuria, and hypoalbuminemia; it is indicative of renal dysfunction. "To date, no patients with TRIM8 variants who presented with nephrotic syndrome but without neurological manifestations have been described." (PMID 34930159, 2021).
neurotoxicity (1 paper, 2022). Toxicity that causes injury to the central or peripheral nervous system or damages its function. "The third module included 3 genes in Neurotoxicity (Itpr1, Trim8, Lrp1), 4 in Blood–brain barrier (Ptpn23, Claudin5, Plectin, Mmp2) and 4 in Cognitive function (Slc8a3, Srf, Nf1, Ncam1)." (PMID 35899365, 2022).
non-small cell lung carcinoma (1 paper, 2025). A group of at least three distinct histological types of lung cancer, including non-small cell squamous cell carcinoma, adenocarcinoma, and large cell carcinoma. "Our findings definitively indicate that TRIM8 constrains the progression of non-small cell lung cancer by facilitating the degradation of MYOF in the cytoplasm via K48-linked ubiquitination." (PMID 39934162, 2025). "While this study provides novel insights into the mechanism by which TRIM8 regulates MYOF to affect the progression of non-small cell lung cancer, the precise role of TRIM8 as a tumour suppressor within the nucleus and its regulation of the MYOF mRNA remain to be elucidated." (PMID 39934162, 2025). "Here, we report that TRIM8, a member of the TRIM family and an E3 ligase, can act as a tumour suppressor in non-small cell lung cancer (NSCLC)." (PMID 39934162, 2025).
Obesity (1 paper, 2023). Accumulation of substantial excess body fat. "Increased expression of TRIM8 can activate liver inflammation, disrupt lipid metabolism homeostasis, and promote the progression of obesity-induced MAFLD, while the absence of TRIM8 has a protective effect on these pathophysiological processes." (PMID 37867509, 2023).
ovarian carcinoma (1 paper, 2024). A malignant neoplasm originating from the surface ovarian epithelium. "This study is the initial demonstration of the cancer‐promoting effects of TRIM8 in ovarian cancer by means of a distinct mechanism that involves the regulation of VDAC2." (PMID 38881325, 2024). "TRIM8 was silenced or overexpressed in ovarian cancer cell lines, with cell proliferation and migration evaluated by CCK8, transwell and clonal formation assays." (PMID 38881325, 2024). "The aim of this study was to explore the specific mechanism by which TRIM8 regulates ovarian cancer." (PMID 38881325, 2024). "TRIM8 promoted the proliferation and migration of ovarian cancer cells in vitro and the growth of subcutaneous tumors in mice in vivo." (PMID 38881325, 2024). "The effect of TRIM8 on ovarian cancer cells in vivo was assessed by subcutaneous tumor formation experiments in nude mice." (PMID 38881325, 2024). "TRIM8 promotes ovarian cancer proliferation and migration by targeting VDAC2 for ubiquitination and degradation, these finding may provide new targets for the treatment of ovarian cancer." (PMID 38881325, 2024). "We used bioinformatics analysis to screen for high expression of TRIM8 in ovarian cancer." (PMID 38881325, 2024). "TRIM8, is involved in the development of various tumors, but its precise regulatory role in ovarian cancer is still unknown." (PMID 38881325, 2024). "Knockdown of VDAC2 increased the resistance of ovarian cancer cells to iron death, whereas overexpression of VDAC2 attenuated ovarian cancer progression induced by TRIM8 overexpression." (PMID 38881325, 2024). "TRIM8 degraded VDAC2 through the ubiquitination pathway, increased the resistance of ovarian cancer cells to iron death, and promoted the proliferation and migration of ovarian cancer." (PMID 38881325, 2024).
renal oncocytoma (1 paper, 2014). "Importantly, no alterations in TRIM8 expression were observed in renal oncocytoma samples compared to non-tumour tissue." (PMID 25277184, 2014).
renal tumour (1 paper, 2014).
viral infections (1 paper, 2025). "Tripartite motif 8 (TRIM8) has been shown to play multiple roles in the host’s defence against viral infections." (PMID 39819815, 2025). "To investigate the functions and underlying mechanisms of TRIM in response to PEDV infection, we knocked out and overexpressed TRIM8 in host cells to test its effects on viral infection." (PMID 39819815, 2025).
tumor (35 papers, 2010 to 2025). "In a transcriptome-wide analysis of Larynx Squamous Cell Carcinoma (LSCC), the most frequent neoplasm of the head and neck, TRIM8 down-regulation was found to be associated with metastatic progression suggesting its tumour suppressor role." (PMID 29182544, 2017). "In our study, the analysis of the TCGA datasets evidenced a significant increase in the risk of death and disease progression in WHO grade III tumours with the lowest TRIM8 expression levels compared to those with the highest level." (PMID 26077989, 2015). "Our findings not only demonstrate the tumour suppressor role of TRIM8 but also provide evidence for its future clinical application in NSCLC treatment." (PMID 39934162, 2025). "Our findings uncover a novel mechanism by which TRIM8 promotes tumor angiogenesis by regulating tumor cell metabolism and implicates a therapeutic potential to disrupt the connection between metabolism and angiogenesis by inhibiting PGK1 K63 ubiquitination." (PMID 41184227, 2025). "Compared with control mice, mice injected with TRIM8-knockdown GC cells presented significantly decreased tumor progression, as reflected by reduced tumor size and weight." (PMID 41184227, 2025). "Experiments with a xenograft model showed that TRIM8 expression suppresses tumour metastasis in vivo." (PMID 39934162, 2025). "The results showed that the expression of TRIM8 was significantly upregulated in the HCC tissues compared with the surrounding non-tumor liver tissues and normal liver tissues." (PMID 38879600, 2024). "Subsequently, tumor samples were divided into high and low TRIM8 expression groups to better study TRIM8 related genes and molecular characteristics." (PMID 36353542, 2022). "Consistent with our previous result, we observed dramatically lower TRIM8 expression in tumor samples compared to normal samples in all of three cohorts." (PMID 35368651, 2022). "In this review, we summarize how the association between these different pathways reflects a dual role of TRIM8 in cancer as an oncogene or a tumor suppressor gene." (PMID 35565438, 2022). "In this review, we also summarized how the association between these different pathways reflects a dual role of TRIM8 in cancer as an oncogene or tumor suppressor gene." (PMID 35565438, 2022). "It has been demonstrated that miR-17-5p and miR-106b-5p directly target the 3′UTR of TRIM8 and repress its expression as well as other tumor suppressors, such as p21 and PTEN." (PMID 36497215, 2022). "TRIM8 has been shown to play a role both as an oncogene and as a tumor suppressor, thus allowing the proliferation of cancer cells." (PMID 35565438, 2022). "In conclusion, TRIM8, among all miR-17-5p targets, is pivotal in controlling cell sensitivity to chemotherapy and its role in tumor growth has been demonstrated also in human tumor xenografts generated in nude mice." (PMID 33673719, 2021). "Specifically, in this review we reported the tumor suppressor role of TRIM8 in the resistance to drugs administered for the treatment of CRC." (PMID 33673719, 2021). "TRIM8 downregulation was associated with metastatic progression in Larynx Squamous Cell Carcinoma (LSCC), the most frequent neoplasm of the head and neck." (PMID 33807506, 2021).
tumor (continued). "Alternatively, the low expression of the tumor-suppressive TRIMs is inversely correlated with specific micro RNAs (miRs) overexpression (e.g., TRIM8 vs. miR17-92 family)." (PMID 33673719, 2021). "Although a role of TRIM8 as an oncogene is reported by affecting the NF-κB and JAK-STAT pathways, much experimental evidence support a role for TRIM8 as a tumor suppressor." (PMID 33673719, 2021). "This dual role of TRIM8 demonstrates an enhanced activity in the inhibition of tumor development and therefore in the role played in chemoresistance and offers more possible therapeutic benefits." (PMID 33673719, 2021). "Since miR-665 mimics modulated human LUSC cell proliferation, cell cycle and apoptosis, TRIM8 was affirmed as a direct target of miR-665, thus, TRIM8 was silenced in NCI-H226/SK-MES-1 cells by siRNA to confirm its involvement in the pro-tumor roles of miR-665." (PMID 33858426, 2021). "In contrast, TRIM8 is an exception, which can function as both a tumor suppressor and an oncogenic molecule." (PMID 33923045, 2021). "The TRIM8 liaison with these three pathways determines its dual role in cancer as oncogene or tumor suppressor functions." (PMID 33807506, 2021). "Deletion of a locus on 10q24.32 containing SUFU (Suppressor of Fused), ARL3 (ADP Ribosylation Factor Like GTPase 3) and TRIM8 (Tripartite Motif Containing 8) was observed in 25/118 tumours (21%)." (PMID 34580349, 2021). "Recently, we reported that TRIM8 is a ‘molecule of duality’ (MoD) because of its dual role as both a tumor suppressor and an oncogenic molecule." (PMID 33923045, 2021). "Remarkably, we have shown that TRIM8 is able to increase the cellular responses to UV, Nutlin-3, and cisplatin in different tumor cells, thereby playing a critical role in the outcome of DNA damaging agents treatment." (PMID 31781486, 2019). "The TRIM8 gene maps on chromosome 10 within a region frequently found deleted and rearranged in tumours and transcribes a 3.0-kB mRNA." (PMID 29182544, 2017).